MIR664B (microRNA 664b)
Synonyms: hsa-mir-664b; MIR644B; mir-664b
Gene: MicroRNA gene on chromosome X (154,768,596 to 154,768,656, forward strand). Ensembl gene ENSG00000284450.
Gene Ontology:
Biological process: RNA processing
Cellular component: nucleolus